NANOG (Nanog homeobox)
Diseases named in the same sentence as NANOG in open-access papers (continued):
Sharing a sentence is not in itself a finding about the gene and the disease.
cancer (continued). "In addition, MPC1 deficiency significantly increased cancer stem cell markers such as Nanog homeobox (NANOG), octamer-binding transcription factor 4 (OCT4), and SRY-box transcription factor 2 (SOX2) in LUAD cells in vivo." (PMID 34059057, 2021). "Treatment resistance of lethal tumors was linked to OCT4, SOX2, and NANOG in cancer patients." (PMID 34452555, 2021). "Moreover, NANOG expression has also been associated with a better or worse prognosis in different cancers, including OSCC." (PMID 32635524, 2020). "Indeed, several reports have shown that NANOG is abnormally increased and is closely associated with poor clinical outcomes in various types of cancer." (PMID 31151327, 2019). "Based on these findings, we analyzed the NANOG DNA sequence associated exosomes derived from a variety of cell sources to identify characteristics that could serve as diagnostic markers of cancer." (PMID 29787607, 2018). "NANOG is expressed in various human cancers and is associated with poor prognosis." (PMID 29907133, 2018). "Thus, our finding of the existence of exosomal NANOG DNA allows for the potential to develop unique diagnostic tools for cancer in restricted locations (i.e. GBM)." (PMID 29787607, 2018). "These suggest that an overexpression of embryonic stem cell associated proteins such as NANOG may be an essential modulator of cancer cell drug-resistance mechanisms, which also contributes to prevent differentiation in CSCs." (PMID 27207017, 2016). "OCT4 and NANOG expression have also been found associated with CSC properties in human cancers." (PMID 24023739, 2013). "Additionally, sex-determining region Y-box transcription factor 2 (SOX2) and NANOG, which are markers of cancer stem cells, have been implicated in ESCC progression, but their regulation through PP1γ and YAP1 remains unclear." (PMID 40626009, 2025). "Selected miRNAs including miR-27a, miR-34a, miR-128, miR-145, miR-150, and miR-335 may act as tumor suppressors, because they have already been associated with direct or indirect regulation of NANOG expression and epithelial-mesenchymal transition regulation in various cancers." (PMID 32733958, 2020). "We observed enrichment of human embryonic stem cell pluripotency genes along with transcriptional regulation of pluripotent stem cells that might lead to activation of POU5F1 (OCT4), SOX2, CD44, NANOG, and other genes associated with self-renewal and drug resistance of cancer cells." (PMID 33339129, 2020). "OCT4 and NANOG were considered key stemness-related transcription factors due to their well-established roles in maintaining pluripotency and cancer stem cell phenotypes in OC." (PMID 41596471, 2026). "Our data adds to the current literature that also suggests higher rates of SOX2 and NANOG in metastatic DSRCT compared to primary cancer." (PMID 41614915, 2026). "Cancer stem-like cells phenotype is regulated by a set of CSC-associated transcription factors including c-Myc, OCT4, SOX2 and NANOG which are known to drive cancer progression." (PMID 40136647, 2025). "Based on our results, we can suggest that the depletion of NANOG or STAT3 through RNAi results in the sensitization of cancer cells to therapeutic agents." (PMID 40729003, 2025). "It is also worth flagging that RNA interference has been applied in NANOG silencing to reduce the proliferation, migration, and metastasis of cancer cells." (PMID 40729003, 2025). "The overexpression of STAT3, or the re-expression of NANOG, has been observed in a variety of cancer cells." (PMID 40729003, 2025). "It has been shown that activation of the IGF1R–/PI3K/AKT pathway increases the expression of cancer stemness markers NANOG and SOX2." (PMID 40243906, 2025). "Studies indicate that 3D cultures better mimic the tumor microenvironment (TME) and enhance cancer stem cell maintenance, partly through the upregulation of stemness-associated transcription factors such as SOX-2 and NANOG." (PMID 41502502, 2025).
cancer (continued). "The hypoxia-associated signaling pathways can trigger the HIF-dependent expression of molecules like KLF4, MYC, OCT4, SOX2, and NANOG, which can enhance cancer stemness and inhibit cancer cell differentiation." (PMID 39928285, 2025). "IGF‐1 treatment activates IGF/IGF‐1R signaling in HBV‐positive HCC cells, increasing expression of cancer stemness markers like nanog homeobox (NANOG) and octamer‐binding transcription factor 4 (OCT4)." (PMID 40060195, 2025). "ARID1A overexpression resulted in a more differentiated ovarian cancer cell line and upon knockdown, the same cancer cell lines started expressing cancer stem cell markers: NANOG, OCT3/4, and SOX2." (PMID 40429787, 2025). "Studies have found that simply high expression of NANOG can induce the differentiation of tumor cells into iPSCs and regulate the self-renewal of cancer stem cells." (PMID 41264633, 2025). "It has been observed that stem cells and transcription factors such as OCT-4, SOX-2, or NANOG play a role in the development of chemoresistance in cancer cells, particularly CSCs." (PMID 40729003, 2025). "The silencing of NANOG expression by RNA interference (RNAi) leads to cell cycle arrest, inhibition of tumour growth, enhancement of apoptosis, inhibition of cancer cell migration and invasion, and an increase in chemotherapy effects." (PMID 40729003, 2025). "These SEs regulate key pluripotency genes, such as OCT4, SOX2, and NANOG, thereby maintaining a stem-like cancer cell state." (PMID 40722714, 2025). "Further investigation can be conducted to assess the impact of specific TFs, such as POU5F1 and NANOG, in cancers occurring in the testis and lung." (PMID 41465103, 2025). "Among the YTHDC2 associated and cancer-related genes (CRGs), CHD1 regulates WNT signaling, EMT and pluripotency genes like SOX2 and NANOG." (PMID 41145440, 2025). "We studied their influence on the expression of STAT3 and NANOG, which play a confirmed role in different stages of cancer development." (PMID 40729003, 2025). "The self-renewal and survival of cancer stem cells (CSCs), responsible for tumor initiation, are promoted by NANOG." (PMID 41465103, 2025). "TB induced G2/M cell cycle arrest, promoted apoptosis via Bax and Caspase-3 activation, and suppressed cancer stem cell markers (NANOG, OCT4, SOX2)." (PMID 41304910, 2025). "Understanding NANOG gene expression and its regulation is a key step in understanding early embryogenesis, pluripotent cell development, and cancer cell proliferation." (PMID 41264633, 2025). "The approach adopted in this study is a two-pronged strategy that involves the silencing of both STAT3 and NANOG, which are transcription factors that have been shown to cooperate in the maintenance of cancer cell progression and chemoresistance." (PMID 40729003, 2025). "NANOG regulates various aspects of cancer development, such as tumor cell proliferation, migration, EMT, immune evasion, drug resistance, malignant transformation, and communication between cancer cells and the surrounding stroma." (PMID 41264633, 2025). "In this study, we examined two proteins, SOX2 and NANOG, which are involved in the growth and survival of cancer stem cells." (PMID 40227667, 2025). "It has been observed that there appears to be a significantly higher expression of NANOG in cancer stem cells (CSCs) than in other tumour cells." (PMID 40729003, 2025). "First, we measured cancer stem-like phenotype markers, including NANOG, NOTCH, POU5F1(OCT3/4), SOX2, and BMI-1." (PMID 39728923, 2024). "Enhanced cell proliferation, accelerated migration and invasion of cells, chemoresistance, adaptation to hypoxia, and immunological evasion of cancer cells are all mediated by NANOG." (PMID 38846985, 2024). "Novel in vitro cancer stem cell-like (CSC-like) culture conditions increase the expression of stemness markers (SOX2, NANOG) and reduce DSRCT cell line susceptibility to chemotherapy while maintaining the ability of DSRCT cells to form xenografts." (PMID 38177125, 2024).
cancer (continued). "NANOG is currently considered an oncogene involved in the main processes of cancer cell proliferation, but also in EMT and metastatic evolution." (PMID 39451527, 2024). "We analyzed data of ER+ BC patients from three large cancer datasets to assess the expression of three pluripotency markers (NANOG, SOX‐2, and OCT4), and the stem cell marker ALDH1A1." (PMID 38400679, 2024). "In this section, we briefly discuss the function of specific stemness factors, such as OCT4, SOX2, and NANOG, which are involved in ROS homeostasis, such as the aryl hydrocarbon receptor (AhR)–Nrf2 axis in cancer development." (PMID 38791215, 2024). "In this study, we analysed the expression of microRNAs (miRNAs) that are regulated by NANOG in TGCTs via integrated bioinformatic analyses of data from The Cancer Genome Atlas and NANOG chromatin immunoprecipitation in human embryonic stem cells." (PMID 38693576, 2024). "Elevated values of NANOG especially in cancer cells were described by previous research, which means that the NANOG gene is a critical member of cancer stem cells." (PMID 38558704, 2024). "In several other cancer types, NANOG overexpression was correlated with increased metastatic potential and proliferation in cancer." (PMID 38760583, 2024). "Loss of cancer differentiation from luminal-like to stem-like is mediated by the activation of stem cell transcription factors (scTF) such as LIN28A, NANOG, POU5F1 and SOX2." (PMID 38595814, 2024). "Subsequently, this work examined MIR‐766‐3P's impact on cancer stem cell (CSC) marker levels and genes associated with CSC, like OCT4, CD133, SOX2, and NANOG." (PMID 39692209, 2024). "NANOG is one of the primary transcription factors responsible for the pluripotency in pluripotent and cancer stem cells." (PMID 38846985, 2024). "Among these markers, NANOG is a transcription factor key to the stemness of cancer stem cells because it induces self-renewal, invasiveness, and chemoresistance of cancer cells through multiple pathways." (PMID 38468952, 2024). "NANOG has been described in the context of CSCs and drug resistance in various cancers, and it has also been shown that its overexpression was associated with an increased ability to form spheroids in vitro." (PMID 39175042, 2024). "Nanog homeobox transcription factor (NANOG) is pivotal for maintaining the stemness and pluripotency of cancer stem cells, as well as their self-renewal capabilities." (PMID 39044249, 2024). "The pluripotent transcription factor NANOG is a stem cell marker that has been reported to regulate cell stemness in various cancers." (PMID 38233377, 2024). "This study identifies the presence of cancer stem cells using immunohistochemical expression of NANOG in OSCC, compared with OED and normal mucosa." (PMID 38558704, 2024). "In the clinic, targeting NANOG is promising as its expression is relatively limited to for instance embryonic development, and cancer cells." (PMID 38760583, 2024). "The higher expression of NANOG was reported in precancer and cancer tissue, contrary to the normal mucosa, what suggests its role in HNSCC tumorigenesis." (PMID 37626893, 2023). "Overexpression of NANOG promotes EMT, cell migration, and invasion in OC and is often associated with high-grade cancers, serous histological subtypes, reduced chemosensitivity, and poor overall and disease-free survival." (PMID 37445860, 2023). "NANOG has been found as overexpressed in many types of human cancers, including the head and neck, liver, lung, kidney, oral cavity, pancreas, prostate, ovary, and other organs." (PMID 37189618, 2023). "Head and neck CSCs express the same profile of proteins as those that regulate embryonic stem cells (ESCs), in particular OCT4, SOX2, and NANOG, which were also reported to be expressed in various cancer tissues and were correlated with poor prognosis." (PMID 37626893, 2023). "The expression of the cancer stem cell markers SOX2, OCT4, and NANOG also has been also associated to these features." (PMID 36968194, 2023).
cancer (continued). "It has been reported that NANOG is a key regulator and transcription factor of CSCs and is upregulated in various human cancers." (PMID 37047234, 2023). "Cancers that express NANOG demonstrate greater aggressiveness compared to those lacking NANOG expression." (PMID 37372456, 2023). "NANOG, a crucial transcription factor in embryogenesis and tumorigenesis, is overexpressed in most cancer stem cells (CSCs)." (PMID 36831547, 2023). "SOX2 was required in early-stage ADC and SCLC, whereas OCT3, KLF4, and NANOG participate other cancer types." (PMID 36717865, 2023). "OLFM4 functions in intestinal stem cells and CSCs and is related to cancer progression as a cancer-promoting factor, the features of which are partially similar to those of NANOG." (PMID 36831547, 2023). "We showed that NANOG conferred anti-apoptotic phenotypes in response to anti-cancer agents by promoting autophagic EGF secretion in therapeutic-resistant tumor cells." (PMID 37165076, 2023). "Compared to monolayer cultures, NB spheroids were characterized not only by significantly higher expression of a subgroup of CSC markers, including CXCR4, NANOG and BMI1, but also increased T389 phosphorylation of cancer-associated RNA-binding protein La." (PMID 36980635, 2023). "Further molecular mechanism found that cancer stemness-related proteins including NANOG, OCT4, SOX2 were dramatically downregulated." (PMID 37149661, 2023). "Understanding the role of NANOG in CSCs has implications for developing targeted therapies and improving cancer treatment outcomes." (PMID 37987305, 2023). "We observed that IL-6 promoted cancer stemness, as evidenced by the dramatic increase in NANOG expression." (PMID 37987305, 2023). "In our previous studies, we profiled the levels of NANOG protein in a variety of human cancer cells." (PMID 37165076, 2023). "NANOG is critical in inducing and maintaining pluripotency in cancer cells thus the paralleled inhibition of GATA4 in week 1 likely reflects the enrichment of CSCs and PGCCs." (PMID 37932310, 2023). "The pluripotency markers NANOG and the Yamanaka factors OCT4, SOX2, KLF4 and c-MYC have previously been shown to be linked with enhanced cancer stem cell properties in cancer cells." (PMID 37950151, 2023). "High NANOG expression is correlated with tumor progression and poor differentiation in various cancers." (PMID 36831547, 2023). "Transformation/transcription domain-associated protein (TRRAP) has been reported to stimulate the tumorigenic potential of cancer cells and induce the gene transcription of NANOG." (PMID 37047234, 2023). "Combined colchicine with lenvatinib demonstrated better anti-cancer effects than either colchicine or lenvatinib alone in view of an anti-proliferative effect and the expressions of NANOG and lenvatinib target genes." (PMID 37894463, 2023). "For example, genes encoding chromatin regulators involved in pluripotency, OCT4, SOX2, KLF4, NANOG, and LIN28, are rarely mutated, but frequently overexpressed in cancer, thus rendering pharmacologic interventions challenging." (PMID 36919699, 2023). "A correlation analysis showed that MBL2 was significantly negatively corr elated with cancer stem cell-related markers, such as NANOG and SOX9." (PMID 37835594, 2023). "NANOG is a cancer stem cell marker which has been shown as a hazard factor to predict poor prognosis in patients with HCC." (PMID 37894463, 2023). "Taken together, these data suggest that TAZ and NANOG regulate cancer stemness and chemosensitivity via SOX2 and OCT4." (PMID 36646707, 2023). "Ongoing animal experiments using siNanog or shNanog have shown the promising therapeutic potential of NANOG targeting in several types of cancer." (PMID 37987305, 2023). "Activation of TLR2/TLR4 aids in tumor progression by inducing the expression of genes associated with stemness i.e OCT 4, NANOG and SOX 2 in cancer cells." (PMID 37954619, 2023).
cancer (continued). "Cancer cells with NANOG expression are considered cancer stem cells, also known as tumor-initiating cells or cancer cells with stem cell-like properties." (PMID 37894463, 2023). "The relative gene expression of the stem cell markers OCT4, SOX2, and NANOG was evaluated to confirm the cancer stem cell features of the CD44+ cells." (PMID 36902135, 2023). "Collectively, these data suggested that targeting TAZ or NANOG inhibits cancer stemness and improves chemosensitivity in vivo." (PMID 36646707, 2023). "Among them, transcriptional factor NANOG is known to high expressed in various cancer cells and acts as an essential modulator of CSCs." (PMID 37283789, 2023). "Meta-analysis also showed that patients with a positive NANOG expression of cancer cells in an HCC tumor had poor 3-year and 5-year overall survival and disease-free survival rate." (PMID 37894463, 2023). "An RT-qPCR assay confirmed that the cancer stem-associated transcripts SOX2, OCT4, and NANOG were substantially upregulated by SFRP1 exposure, in both LNCaP and DU145." (PMID 36968194, 2023). "Whereas NANOG function has been extensively characterized in cancers, mainly for its expression and activity in cancer stem cells (CSCs), less is known about VENTX." (PMID 35892595, 2022). "Like the master regulators OCT4, SOX2, and NANOG, multiple molecular signaling pathways that regulate cellular pluripotency are also dysregulated in cancer." (PMID 36118530, 2022). "The pluripotency transcription factor NANOG, known as a key regulator of embryonic development and cellular reprogramming, has been reported to be broadly expressed in human cancers." (PMID 35104240, 2022). "In esophageal squamous cell carcinomas (ESCCs), the knockdown of NANOG clearly reduced cancer cell proliferation and the ability to resist drugs." (PMID 36497144, 2022). "On the other hand, over-expression of NANOG in colorectal CSCs promotes colony formation and tumourigenicity in vivo, and NANOG-shRNA transduced cancer cells exhibit decreased clonogenic growth and reduced proliferation." (PMID 36566021, 2022). "In this respect, we noted that immune pressure imposed by antigen (Ag)-specific CTLs drives the acquisition of NANOG, a master TF that mediates the emergence of a stem-like cancer cell state and immune evasion." (PMID 35606403, 2022). "POLR3G embryonic regulators OCT4 and NANOG, for example, are markers of cancer stem cells and play important roles in tumor-initiating cells." (PMID 36710885, 2022). "The transcription factor NANOG plays a role in embryonic stem cell self‐renewal and is essential for maintaining cancer stem cell properties." (PMID 36114703, 2022). "In this study, we found that NANOG was associated with an immune-refractory feature of the TME and poor clinical outcomes in patients with cancer and that NANOG expression influenced the sensitivity of tumor cells to HDAC1 inhibitors." (PMID 35104240, 2022). "In general, cancer stem cells usually express some of the transcription factors associated with pluripotency, such as SOX2, NANOG and OCT4)." (PMID 35954194, 2022). "Further, to our knowledge, we are the first to report the role of the NANOG/HDAC1 axis in ICB therapy–refractory cancer." (PMID 35104240, 2022). "Comparative transcriptome analysis using The Cancer Genome Atlas (TCGA) data revealed a positive correlation between the NANOG signature and CD59 mRNA levels in multiple human cancer types." (PMID 35606403, 2022). "miR-26a-5p overexpression suppressed the protein levels of OCT4, NANOG, and SOX2, and embryonic stem cell markers are associated with cancer stem cells, while miR-26a-5p inhibition promoted the expression of these markers." (PMID 35860691, 2022). "CD24 in combination with CD44 and/or CD133 (PROM1) has been highlighted as cancer stem cell markers (in combination with NANOG, OCT3/4, and SOX2), and a cell‐type‐dependent correlation of CD24 to the chemokine receptor CD184 (CXCR4) has been shown." (PMID 34293822, 2022).